KLF4 (KLF transcription factor 4)
Diseases named in the same sentence as KLF4 in open-access papers (continued):
Sharing a sentence is not in itself a finding about the gene and the disease.
tumor (continued). "Additionally, a study has revealed that LINC01915, a type of long non-coding RNA, inhibited the uptake of TEVs by normal fibroblasts (NFs), cancer-associated fibroblasts (CAFs) activation, and tumor angiogenesis through the miR-92a-3p/KLF4/CH25H axis, thereby impeding tumor growth." (PMID 37720208, 2023). "Furthermore, staining for vimentin, another mesenchymal marker, showed a lack of expression within the epithelial component of the normal-appearing mucosa [SB474N], but a slight increase within the epithelial compartment upon loss of KLF4 in the tumor tissues [SB474T, white arrowheads]." (PMID 32566755, 2019). "While initially characterized as a tumor suppressor, the functional landscape of KLF4 is far more nuanced." (PMID 41532367, 2026). "Krüppel‐like factor 4 (KLF4) exhibits a dual, context‐dependent role, acting as both a tumor suppressor and an oncogene." (PMID 41532367, 2026). "Under the influence of tumor‐secreted factors, KLF4 expression is upregulated in pericytes, which drives them toward a less differentiated state." (PMID 41532367, 2026). "In recent years, increasing attention has shifted toward viewing these seemingly contradictory roles of KLF4 through the lens of the tumor microenvironment (TME)." (PMID 41532367, 2026). "Beyond its role in NK cell development and maintenance, KLF4 emerges as a critical orchestrator of NK cell‐mediated tumor immune surveillance, particularly through the immunoreceptor NKG2D, which is expressed on NK cells and subsets of T cells." (PMID 41532367, 2026). "KLF4 acts as a tumor suppressor by directly binding to the CXCL8 promoter and repressing its transcription, leading to reduced CXCL8/CXCR1/2‐mediated MDSC chemotaxis." (PMID 41532367, 2026). "Even within the same cancer types, KLF4 can exhibit contradictory effects, further emphasizing the complexity of its involvement in tumor biology." (PMID 41532367, 2026). "By modulating KLF4 expression or activity, there is hope to reshape the anti‐tumor immune function of T cells." (PMID 41532367, 2026). "Research also shed light on the critical role of KLF4 in plasma cell maturation, with implications for anti‐tumor immunity." (PMID 41532367, 2026). "This review aimed to comprehensively summarize the roles of KLF4 in the tumor microenvironment (TME) and evaluate its potential as a therapeutic target." (PMID 41532367, 2026). "Despite these challenges, the potential of KLF4 as a biomarker for tumor diagnosis and prognosis remains a compelling area of investigation." (PMID 41532367, 2026). "CPTAC datasets were utilized for three types of tumors (HNSC, LUAD, and PAAD) to compare KLF4 total protein levels between normal and primary tumor tissues." (PMID 40299916, 2025). "Further, KLF4-ChiP assays of the CD200 promoter in D2A1 tumor cells with KLF4 overexpression revealed that KLF4 protein was enriched at −200~+30bp region of the CD200 promoter." (PMID 40568095, 2025). "KLF4 is an environmentally dependent transcription factor that acts as a tumor suppressor or oncogene, exerting anti-cancer effects by increasing cell proliferation, metabolism, and reducing ROS through the molecular pathway of glycolysis." (PMID 40276761, 2025). "High expression of KLF4 accelerates LSEC aging, which promotes tumor cell migration through the senescence‐associated secretory phenotype and induces a local immunosuppressive TME." (PMID 40027151, 2025). "The ability of CSCs to prevent ubiquitination of KLF4, and thus enhance tumor metastasis, is a specific target for future therapeutic intervention." (PMID 40868290, 2025). "These divergent effects were underpinned by organ-biased differences in the tumor cells’ chromatin state that emerged in the premalignant pancreas and were distinguished by the dominance of KLF4 versus RUNX1 transcription factors." (PMID 40999053, 2025).
tumor (continued). "In line with its role in inhibiting cell division in normal T cells, KLF4 functions as a tumor suppressor in leukemic T cells by repressing a kinase that drives T-ALL cell proliferation." (PMID 40589762, 2025). "This study identifies ACTL6A as a pivotal epigenetic regulator of chromatin accessibility and transcriptional repression in CRC through its inhibitory effect on KLF4, a tumor-suppressive TF." (PMID 40877226, 2025). "KLF4 expression was frequently found to be lost in various human cancer types, and its low expression in tumors supports its tumor-suppressive function." (PMID 41463190, 2025). "The duality of KLF4, acting as either a tumor promoter or a tumor suppressor, has been reported by several authors, as summarized above in the present manuscript." (PMID 40863723, 2025). "Studies have shown that co-treatment with the tyrosine kinase inhibitor imatinib and KLF4 overexpression enhances apoptotic effects, suggesting their synergistic role in promoting tumor cell death." (PMID 39995670, 2025). "circLECRC and KLF4 work together as tumor suppressors by inhibiting YAP1 hyperactivation and eventually its downstream pathway (EGFR, MYC, BIRC5, and CTGF)." (PMID 40863723, 2025). "Krüppel‐like factor 4 (KLF4) exhibits both oncogenic and tumor‐suppressive effects depending on the type of cancer and cellular context." (PMID 40354086, 2025). "In CRC, KLF4 can act as a tumor suppressor through inducing apoptosis and inactivating WNT pathway in the early stage, but also as an oncogene through inducing stemness in the late stage, suggesting its context‐dependent role." (PMID 40066228, 2025). "KLF4 plays a promoter role in tumorigenesis and development, or tumor suppressor as a context-dependent anti- and pro-inflammatory factor." (PMID 39995670, 2025). "Specifically, the circRNA CDR1 is highly expressed in HB cells and inhibits the expression of the stem cell maintenance factor KLF4 by acting as a sponge for miR-7–5p, thereby promoting the proliferation and maintenance of the stemness of tumor cells." (PMID 41393242, 2025). "This is particularly significant as MDSCs are known to undergo extensive epigenetic reprogramming in response to tumor-derived signals, suggesting that KLF4’s activity in this context is likely modulated by chromatin accessibility and histone modifications." (PMID 40552304, 2025). "NF2 tumours exhibited more immune cells than AKT1 E17K or KLF4 K409Q, and AKT1 E17K showed slightly higher immune cell counts than KLF4 K409Q." (PMID 40420192, 2025). "When focusing on regulatory patterns, we found that CAFs displayed distinct cell type-specific TFs alongside shared TFs widely involved in carcinogenesis, including various tumor promoters or tumor suppressors, such as KLF4, NFIA, TCF21, NFKB1, and EGR1." (PMID 39872221, 2025). "CSC biology is regulated by interconnected networks, including pluripotency transcription factors (OCT4, SOX2, Nanog, KLF4, Myc), intracellular signaling pathways (Wnt, NF-κB, Notch), epigenetic mechanisms, the tumor microenvironment, and EMT processes." (PMID 41204384, 2025). "KLF4 mRNA expression in the TCGA-COAD dataset was examined to investigate the role of KLF4 in colon tissue samples; its expression was lower in tumor tissues than in normal tissues, supporting its potential relevance in CRC." (PMID 40877226, 2025). "Given β-glucan’s dual role in innate memory and tumor suppression, the KLF4 axis presents a compelling therapeutic target; further investigation into KLF4 as a target for cancer immunotherapy is warranted." (PMID 40552304, 2025). "KLF4 can affect tumor immunity and responses to cancer therapies, including newly promising ICIs, by modulating macrophage phenotypes between pro- and anti-inflammatory states." (PMID 40552304, 2025). "IFN-γ in turn induced KLF4-mediated expression of SLURP1 that is critical in promoting tumor dormant state." (PMID 40568095, 2025).
tumor (continued). "Our results indicate that KLF4 plays a crucial role in maintaining genetic stability by enhancing cell DDR, supporting previous findings that KLF4 functions as a tumor suppressor." (PMID 40699616, 2025). "We show that abrogation of myeloid TGF-β signaling induced an IFN-γ rich immune milieu, leading to KLF4-SLURP1 upregulation that facilitates the tumor dormant state." (PMID 40568095, 2025). "These layers of post-transcriptional downregulation thus point to a tumor-promoting and radioresistance-promoting role of KLF4 in CRC, at variance with previously published data on this neoplasy." (PMID 40863723, 2025). "KLF4 is also a tumor suppressor or an oncogene acting in a tissue dependent manner by regulating the expression of specific genes in distinct cell types and exhibiting pro- or anti-apoptotic functions." (PMID 40006984, 2025). "Studies have shown that the circRNA CDR1as promotes tumor stem cell characteristics and tumor progression by sponging miR-7–5p to regulate the expression of Kruppel-like factor 4 (KLF4)." (PMID 41393242, 2025). "circRNAs act as sponges for miRNAs and synergize with KLF4, which can function as either a tumor promoter or suppressor in different tumors." (PMID 40863723, 2025). "KLF4 exhibits a context-dependent dual role in tumor biology, functioning as a tumor suppressor in some contexts while acting as an oncogene in others." (PMID 39995670, 2025). "By sponging miR-9, circPLEKHM3 also suppresses proliferation and migration of ovarian cancer cells through the upregulation of KLF4, which works as a tumor suppressor." (PMID 40863723, 2025). "ACTL6A contributes to CRC cell proliferation by inhibiting the KLF4-mediated transcriptional activation of tumor-suppressive genes." (PMID 40877226, 2025). "The KLF4-assocaited genes that were least correlated with a tumor stimulatory effect for several tumors included TNFRSF18." (PMID 40299916, 2025). "In HER2-positive disease, our findings associate genes such as ARG2, S100A1, MT2A, EIF4EBP1, KLF4, BTG3, and BAG1 to be associated with favourable prognosis through their roles in metabolic regulation, oxidative stress mitigation, and tumour suppression." (PMID 41007296, 2025). "Conversely, KLF4 is a tumor suppressor when regulated by miR-25-3p, miR-29a-3p, miR-135b-5p, miR-1233-3p, and miR-9." (PMID 40863723, 2025). "While the top three KLF4-assocaited genes correlated with a tumor stimulatory effect for several tumors were CX3CL1, TNFRSF4, and IL1A." (PMID 40299916, 2025). "Together, these results suggest a critical role of an IFN-γ-KLF4-SLURP1 axis in the observed tumor dormancy phenotype." (PMID 40568095, 2025). "Previous studies have demonstrated that KLF4 exhibits a cell type-dependent role in either tumor suppression or promotion." (PMID 40299916, 2025). "Abrogation of myeloid-specific TGF-β signaling induced tumor dormancy by promoting an IFN-γ rich tissue microenvironment that activates KLF4-mediated cellular reprogramming." (PMID 40568095, 2025). "This review aims to explore the biological and molecular mechanisms of KLF4 within the immune system, with a particular focus on its interactions with tumor immunity and its dual role as a switchable oncogene/suppressor." (PMID 39995670, 2025). "Among dual-function transcription factors, KLF4, a prominent member of the Krüppel-like factor family, demonstrates this context-dependent dual role in tumor biology and immune system regulation." (PMID 39995670, 2025). "In the GEPIA (Gene Expression Profiling Interactive Analysis) dataset, which contains 33 different tumor types, Nrf2 and KLF4 show a notable positive correlation." (PMID 40755294, 2025). "In BRCA, ATXN3 is significantly upregulated and promotes tumour metastasis and invasion by regulating KLF4." (PMID 40995818, 2025). "These factors significantly upregulate transcription factors such as Sox2, Oct4, Klf4, and Nanog, which are known to reprogram differentiated tumor cells into stem-like phenotypes." (PMID 40253386, 2025).
tumor (continued). "For instance, TFF3 has been associated with epithelial regeneration and cancer metastasis, and KLF4 is known for its dual role in tumor suppression and promotion depending on the cellular context." (PMID 41284725, 2025). "The presence of cancer stem cells in the tumour tissue is further substantiated by increased expression of embryonic-specific transcription factors such as OCT4, SOX2, Nanog, cMYC and KLF4 in tumour tissues." (PMID 40433700, 2025). "KLF4-ChiP assays in D2A1 tumor cells with KLF4 overexpression revealed that KLF4 protein was enriched at the −500~−250 and −150~+30 bp regions of the SLURP1 promoter, consistent with this motif mapping." (PMID 40568095, 2025). "Overall, our results indicate that KLF4 is involved in the DNA repair mechanism as a tumor suppressor gene." (PMID 40699616, 2025). "As CSCs are well-known contributors to cancer recurrence, metastasis, and resistance to chemotherapy tolerance, the central role of KLF4 in CSC regulation underscores its importance in tumor progression and therapy resistance." (PMID 39995670, 2025). "The role of miRNAs in CRC has been extensively reviewed, with mechanisms primarily involving the regulation of tumor proliferation, metastasis, and angiogenesis through KLF4 targeting." (PMID 39995670, 2025). "A recent study using integrative transcriptome and proteome analyses of RCC with a VTT found KLF4 to be one of the differentially expressed genes in the VTT compared to a primary tumour." (PMID 40869272, 2025). "Tumor cells can acquire or reinforce stem-like properties through reactivation of pluripotency-associated transcription factors such as OCT4, SOX2, Nanog, KLF4, and Myc." (PMID 41204384, 2025). "We go into detail here specifically on the axes circRNA/miRNA/KLF4 and their implication in tumor development." (PMID 40863723, 2025). "The interplay between KLF4 and myeloid cells is especially pertinent in the context of cancer, where KLF4’s role in modulating immune responses can influence tumor progression and metastasis." (PMID 40552304, 2025). "The transcription factor STAT5A further suppresses KLF4 transcription, promoting tumor progression, but KLF4 overexpression can counteract the oncogenic effects of STAT5A." (PMID 39995670, 2025). "Research has shown that the expression level of miR-7–5p is negatively correlated with that of KLF4 and that the upregulation of miR-7–5p can inhibit KLF4 expression, thereby suppressing tumor stem cell characteristics." (PMID 41393242, 2025). "Overall, since KLF4 plays a crucial role in regulating macrophage polarization and function, understanding its mechanisms will contribute to the development of new tumor therapeutic strategies." (PMID 39995670, 2025). "In most solid and hematologic malignancies, KLF4 acts as a tumor suppressor by inhibiting cell proliferation and promoting apoptosis." (PMID 39995670, 2025). "Clarifying the spatiotemporal expression and function of KLF4 isoforms in the tumor microenvironment is essential." (PMID 40552304, 2025). "How exactly does KLF4 serve as a critical “bridge” connecting immunity and tumor biology by simultaneously regulating the tumor microenvironment and immune responses?" (PMID 39995670, 2025). "The genetic alteration patterns varied across malignancies, thus highlighting the diverse roles of KLF4 in different tumor contexts." (PMID 40299916, 2025). "Plexin B2 on the surface of hepatocytes activates class IV semaphorin signaling in tumor cells, promoting their epithelialization mediated by Krüppel‐like factor 4 (KLF4)." (PMID 40027151, 2025). "The CPTAC database was employed to identify differential KLF4 total protein expression between various primary and tumor samples." (PMID 40299916, 2025). "In the context of cancer, KLF4 and its interacting molecular pathways exhibit complex, multifaceted roles depending on the type or stage of the tumor." (PMID 39995670, 2025).
tumor (continued). "TCFL5-E8 reduces KLF4 mRNA levels, potentially suppressing its tumor-promoting effects while CHA upregulates KLF4, possibly facilitating tumor progression." (PMID 39995670, 2025). "Some KLFs, like KLF4, are involved in the regulation of apoptosis, sometimes acting as tumour suppressors by promoting apoptosis, while in other instances exhibiting anti-apoptotic effects." (PMID 40831570, 2025). "Depending on the context, KLF4 plays a dual role in cancer, functioning as a tumor suppressor or as an oncogene." (PMID 40552304, 2025). "KLF4 plays a significant role in tumor development; however, its function in specific cancer types is not uniform." (PMID 39944135, 2025). "The LLPS microenvironment driven by the two LCDs of KMT2D facilitates H3K4 histone monomethylation transcription as well as the expression of the tumor-associated TFs LIFR and KLF4, promoting tumor progression." (PMID 40642070, 2025). "KLF4, a Zn finger transcription factor, functions as a tumor suppressor in CRC by upregulating p21WAF1/Cip1 and downregulating cyclin D1, thereby inhibiting cell proliferation and tumorigenesis." (PMID 39335919, 2024). "We found that patients with high expression of KLF4 had a better tumor differentiation status (p = 0.008) and a lower incidence of microvascular invasion (MVI) (p = 0.033)." (PMID 39000273, 2024). "In conclusion, our study demonstrates that KLF4 functions as a tumor suppressor and inhibits the progression of HCC through the miR206/RICTOR axis." (PMID 39000273, 2024). "Conversely, knockdown of KLF4 resulted in increased tumor sizes and weights compared to the control group." (PMID 39000273, 2024). "KLF4 is a crucial regulator of normal cell proliferation and inhibits the proliferation of tumor cells, serving as a suppressor in many cancers." (PMID 39263604, 2024). "To verified the relationship between KLF4 expression and endothelial cell senescence, and how them affect tumor cells, we firstly build an in vitro model." (PMID 38951874, 2024). "miR-152-3p acts as a tumor suppressor along with miR-148-3p by synergistically repressing Kruppel-like factor 4 (KLF-4), thereby regulating cell proliferation, differentiation, and migration." (PMID 38705879, 2024). "These genes exhibit tumor suppressor properties, inhibiting cell growth, DNA synthesis, and cell cycle progression, with KLF4 having dual capabilities in promoting cell survival and counteracting c-Myc-induced programmed cell death." (PMID 39239558, 2024). "Klf4 is a transcription factor acting as an oncogene or a tumor suppressor gene in diverse types of cancers." (PMID 38822350, 2024). "We dissect a mechanism through which plexin B2 interacts with class IV semaphorins on tumour cells, leading to KLF4 upregulation and thereby promoting the acquisition of epithelial traits." (PMID 39048831, 2024). "When GPX8 expression reduces, the expression of tumor stemness markers, such as KLF4, OCT4, and CD133 tend to increase." (PMID 38607517, 2024). "Functional assays, such as CCK-8, EdU, and colony formation, as well as in vivo assays, including subcutaneous tumor formation and liver orthotopic xenograft mouse models, were conducted to determine the impact of KLF4 on HCC proliferation." (PMID 39000273, 2024). "Overall, these evidences confirm the context-dependent role of KLF4 that can act both as a tumor suppressor (as in the case of NHL and CRC) or as a tumor promoter (as in the case of HNSCC)." (PMID 39135777, 2024). "The loss of Klf4 expression, observed in a subset of CRC cases, suggests its role as an early event in tumor development." (PMID 39335919, 2024). "miR-206 promotes M1 polarization of Kupffer cells (KCs) via targeting Klf4, which enhances anti-tumor immunity." (PMID 38866328, 2024).